STAT3 (signal transducer and activator of transcription 3)
Diseases named in the same sentence as STAT3 in open-access papers (continued):
Sharing a sentence is not in itself a finding about the gene and the disease.
autoinflammatory syndrome (3 papers, 2018 to 2025). A group of disorders of the innate immune system characterized by attacks of seemingly unprovoked inflammation without significant levels of either autoantibodies or autoreactive T cells more characteristic of autoimmune disease. "Gain-of-function STAT3 mutations promote monocyte overproduction through hyperactive IL-6/GM-CSF signaling, creating a pro-inflammatory loop in autoinflammatory syndromes." (PMID 41141324, 2025). "That analysis identified 3 factors, IL-6, IL-17, and Stat3, that may serve as therapeutic targets in treatment of auto-inflammatory syndromes." (PMID 30361689, 2018). "For STAT3-mediated conditions, JAK-STAT modulation with ruxolitinib has proven effective in controlling both monocyte overproduction and associated inflammatory cascades, particularly in autoinflammatory syndromes characterized by IL-23/IL-17 axis dysregulation." (PMID 41141324, 2025). "Both RA and auto-inflammatory syndromes develop after birth, and adult-onset animal models relevant to RA, such as CIA and AIA, are available; moreover, the function of IL-17 and Stat3 in RA development has been demonstrated using animal models." (PMID 30361689, 2018).
bile duct cancer (3 papers, 2019 to 2025). "For example, inhibition of STAT3 signalling reduced miR-31 expression and cell proliferation in bile duct cancer cell lines (HuCCT-1 and TFK-1)." (PMID 34716428, 2022). "Furthermore, several studies reported the capacity of luteolin to inhibit STAT3 in different types of cancer cells, including breast, stomach, lung, liver, pancreas, cervix, and bile duct cancers." (PMID 31491838, 2019).
bronchiolitis (3 papers, 2019 to 2024). Inflammation of the bronchioles characterized by swelling of the bronchioles and mucus accumulation. "Despite the predicted downregulation of the pathway, IL-6 was a target of sRNAs associated with RSV-only cases, and therefore there was a higher predicted level of IL-6 and subsequent activation of STAT3 in RV-only bronchiolitis comparatively." (PMID 38410509, 2024). "In RSV-positive infants with bronchiolitis, there was a reduced expression of STAT3 compared to those with bronchiolitis due to other respiratory viruses." (PMID 35406717, 2022). "We found that in infants with bronchiolitis infected with RSV, the expression of STAT3 detected in nasal washes is reduced when compared to that in infants infected by other viruses." (PMID 31780735, 2019). "As STAT3 is an important mediator for CD4+ T cells, CD8+ T cells, and B cell activation and proliferation, this was investigated in the context of RSV-induced bronchiolitis." (PMID 35406717, 2022).
cerebral malaria (3 papers, 2012 to 2019). A sequestration of Plasmodium falciparum in the brain, which can cause coma and/or seizures. "Specifically, STAT3 signaling and NK cell IL-10 production is detrimental to host innate resistance to Lm, but promotes survival in a model of cerebral malaria." (PMID 31552035, 2019). "We first clarified the roles of Heme/HO-1, CXCL10/CXCR3 and STAT3 in CM pathogenesis utilizing a well established experimental cerebral malaria mouse (ECM, P. berghei ANKA) model." (PMID 22479586, 2012). "Our interest in signal transducer and activation of transcription 3 (STAT3) and AKT signaling pathways derives from the reported importance of STAT3 in the pathogenesis of cerebral malaria while AKT activation is a typical downstream signal molecule for NRG-1/ErbB4." (PMID 29636063, 2018). "Recent studies in our laboratory and others have revealed a hitherto unknown correlation between chemokine CXCL10/CXCR3, Heme/HO-1 and STAT3 and cerebral malaria severity and mortality." (PMID 22479586, 2012). "Here, we identified NK cell-intrinsic STAT3 activation as vital for IL-10 production during both systemic Listeria monocytogenes (Lm) infection and following IL-15 cytokine/receptor complex (IL15C) treatment for experimental cerebral malaria (ECM)." (PMID 31552035, 2019).
cerebrovascular diseases (3 papers, 2019 to 2025). "Recently, with the study of cardiovascular and cerebrovascular diseases becoming increasingly popular, STAT3 has been demonstrated to play roles in several cardiovascular diseases, including arteriosclerosis, cardiac hypertrophy, and heart failure 19-22." (PMID 31588227, 2019).
cervical adenocarcinoma (3 papers, 2014 to 2022). An adenocarcinoma arising from the cervical epithelium. "Collectively, these results showed that IL-6 is a potent inducer STAT3 signaling, while it has a weaker effect on the phosphorylation of Akt and ERK in Cervical Adenocarcinoma." (PMID 24533454, 2014).
choriocarcinoma (3 papers, 2017 to 2025). An aggressive malignant tumor arising from trophoblastic cells. "SOCS-3 have been identified as important regulators of ERK/MAPK pathway and STAT3 signaling in undifferentiated Rcho-1 cells, which were derived from rat choriocarcinoma." (PMID 29234375, 2017).
chronic lung disease (3 papers, 2011 to 2025). According to the definitions of the American and British Thoracic Societies, including pulmonary functional tests, X-rays, and CT scans for items such as fibrosis, bronchiectasis, bullae, emphysema, nodular or lymphomatous abnormalities. "IL-6 mediated activation of STAT-3 has been implicated in several diseases; however, little is known about the ability of adenosine to activate this pathway in the context of chronic lung disease." (PMID 21799929, 2011). "Thus, activation of STAT-3 in airway epithelial cells may regulate processes that contribute to distal airway remodeling in these chronic lung diseases." (PMID 21799929, 2011).
cleft palate (3 papers, 2018 to 2023). Cleft palate is a fissure type embryopathy that affects the soft and hard palate to varying degrees. "However, little is known about the possible mechanisms underlying involvement of Stat3 in the pathogenesis of the cleft palate." (PMID 30046048, 2018). "Further investigation to identify individuals with an increased risk of preventable cleft palate is warranted, and mouse models are indispensable for improving our understanding of the JAK2/STAT3 axis." (PMID 37846594, 2023). "Thus, our findings suggested the function of JAK2/STAT3 in palatal fusion and also provided experimental basis for the beneficial use of folic acid for cleft palate." (PMID 37846594, 2023). "Based on these findings, we investigated whether or not folic acid application could rescue the cleft palate caused by AG490 treatment with enhancement of STAT3 activity." (PMID 37846594, 2023). "Furthermore, the rescue of the mutant cleft palate using folic acid might highlight potential therapeutic targets aimed at Stat3 modification for the prevention and pharmaceutical intervention of cleft palate." (PMID 31171577, 2019). "The involvement of Stat3 modification in Runx1-Tgfb3 signaling may offer novel insights into the physiologic and pathophysiologic regulation of the palatal fusion and our study also clarifies potential therapeutic targets in the prevention and pharmaceutical intervention for cleft palate." (PMID 30046048, 2018).
contact dermatitis (3 papers, 2020 to 2025). An inflammatory skin condition caused by direct contact between the skin and either an irritating substance or an allergen. "Moreover, it was recently determined that astrocytes in the dorsal horn of the spine are responsive in atopic and contact dermatitis models through the activation of signal transducer and activator of transcription 3 (STAT3), and contribute crucially to itch." (PMID 40443235, 2025). "In the contact dermatitis mouse model, nuclear translocation of K17 facilitates the activation and nuclear translocation of signal transducer and activator of transcription 3 (STAT3) activating CCL20 production and CD8+ and CD4+ T cell trafficking to skin lesions." (PMID 38730319, 2024).
crescentic glomerulonephritis (3 papers, 2022 to 2024). A histopathologic term for a pattern of diseases characterized by extensive crescent formation in the glomeruli; patients present clinically with rapid deterioration of renal function, and possible progression to end-stage renal failure within weeks or months. "Taken together, glucocorticoids exert therapeutic effect on anti-GBM crescentic glomerulonephritis through inhibiting podocyte EGFR/STAT3 signaling and the downstream pathway that leads to PEC proliferation and crescent formation." (PMID 35223886, 2022). "Meanwhile, the activation of the STAT3 signaling pathway is demonstrated to be critical for the development of crescentic glomerulonephritis, which exacerbates the proliferation of glomerular cells and the damage of kidney." (PMID 36575400, 2022). "Interestingly, Stat3 also programs Th17 lineage‐specific Tregs (another name for Treg/Th17 cells) in crescentic glomerulonephritis which is an inflammatory disorder." (PMID 38415949, 2024). "It appears that the development of crescentic glomerulonephritis may also follow the sequence of EGFR/STAT3/Notch activation, secreted factors expression in podocytes, and Notch activation and cellular proliferation in PECs." (PMID 35223886, 2022).
diabetic foot ulcers (3 papers, 2022 to 2025). "In human diabetic foot ulcers, impairment in GM-CSF activation of signal transducer and activator of transcription 3 (STAT3) expression results in decreased immune cell recruitment." (PMID 36685591, 2022). "Previous reports have indicated that STAT3 is inhibited in diabetic foot ulcers." (PMID 39841618, 2025).
dysplasia (3 papers, 2020 to 2025). A usually neoplastic transformation of the cell, associated with altered architectural tissue patterns. "Patients with IBD and dysplasia show a higher level of activated STAT3 compared to those without dysplasia." (PMID 32863742, 2020). "The level of activated STAT3 in patients with IBD and dysplasia is different from patients with IBD and without dysplasia." (PMID 32863742, 2020).
embryonal carcinoma (3 papers, 2013 to 2016). A non-seminomatous malignant germ cell tumor characterized by the presence of large germ cells with abundant cytoplasm resembling epithelial cells, geographic necrosis, high mitotic activity, and pseudoglandular and pseudopapillary structures formation. "Stat-3 and Ras pathways have been implicated in the control of GATA-4 expression in embryonal carcinoma and ES cells, and experiments using GATA-6 knockout and chimeric mice suggest a cross-regulation between GATA-6 and GATA-4." (PMID 23409073, 2013).
encephalomyelitis (3 papers, 2017 to 2020). Inflammation of the brain and the spinal cord. "We show here that STAT3 deletion in B cells correlated with enhanced inflammation in the brain and spinal cord and correlated with severe encephalomyelitis." (PMID 33004854, 2020). "Also, the knockout mice study of IL-6−/− and STAT3−/− develops encephalomyelitis resistant, which suggests the role of STAT3 in neuropathogenesis." (PMID 31484947, 2019).
endometrioid adenocarcinoma (3 papers, 2019 to 2022). An adenocarcinoma characterized by the presence of malignant glandular epithelial cells resembling endometrial cells. "In fact, a correlation was noted between nuclear Stat3 levels and Cx43 and Cx26 in grade 1 and 2 uterine endometrioid adenocarcinomas, while this association was progressively weaker as the tumors dedifferentiated to G3, presumably due to the activation of additional oncogenes." (PMID 30717267, 2019).
endometritis (3 papers, 2016 to 2025). An acute or chronic, usually bacterial infectious process affecting the endometrium. "Furthermore, these findings could be translated to use of inhibitors of STAT3/IL6R signaling in the uterus to limit the severity of endometritis." (PMID 26813342, 2016).
ependymoma (3 papers, 2012 to 2025). A WHO grade II, slow growing tumor of children and young adults, usually located intraventricularly. "More importantly, a significant increase in activated STAT3 has been reported in the anaplastic histology group (WHO III) with respect to WHO II ependymoma." (PMID 33668642, 2021).
Erythema (3 papers, 2023 to 2024). Redness of the skin, caused by hyperemia of the capillaries in the lower layers of the skin. "However, IL-17A treated STAT3 mice dorsal skin showed erythema and flaky scaling." (PMID 37465147, 2023).
esophageal tumor (3 papers, 2016 to 2021). "Furthermore, the expression of Ki-67 and phospho-STAT3 in orthotopic esophageal tumor tissues were decreased after CYT-Rx20 treatment, in agreement with our in vitro observation." (PMID 27875549, 2016). "CYT-Rx20 suppressed xenografted and orthotopic esophageal tumor growth along with decreased expression of Ki-67, phospho-AKT, and phospho-STAT3 in tumor tissues." (PMID 27875549, 2016).
fibromyalgia (3 papers, 2017 to 2025). A chronic disorder of unknown etiology characterized by pain, stiffness, and tenderness in the muscles of neck, shoulders, back, hips, arms, and legs. "The IL-6 molecule through activating the Jak/STAT3 pathway plays an essential role in fibromyalgia pathogenesis by causing excessive chemokines production and triggering the activation of glial cells." (PMID 39920875, 2025). "In summary, our study showed that IL-6 has a key role in fibromyalgia, activating the Jak/STAT3 pathway, chemokine overexpression and glial-cell activation." (PMID 36979771, 2023). "Furthermore, STAT3 has a key role in nociceptive transmission; in our study, the inhibition of the Jak/STAT3 pathway by the IL-6-R-Ab administration reduced the pain-like behaviors induced by fibromyalgia." (PMID 36979771, 2023).
follicular lymphoma (3 papers, 2017 to 2025). Follicular lymphoma is a form of non-Hodgkin lymphoma characterized by a proliferation of B cells whose nodular structure of follicular architecture is preserved. "By blocking the VEGFR2/ERK/STAT3 signaling cascade, this study recommends the novel multitarget inhibitor chiauranib as a potent anticancer treatment for transformed follicular lymphoma." (PMID 36678513, 2022).
gastrointestinal infection (3 papers, 2015 to 2022). "Gliadins caused phosphorylation of STAT3 in PBMCs, and it can be speculated that constant stimulation of the immune system (e.g., by chronic inflammation or gastrointestinal infection) may alter tightly controlled activation of STAT3 and differentiation of Foxp3+ regulatory T cells." (PMID 36296938, 2022). "In summary, multiple pieces of evidence demonstrate that STAT1 and STAT3 both have essential functions during gastrointestinal infection by orchestrating epithelial barrier integrity." (PMID 34497340, 2022). "In conclusion, we showed that activation of Stat3 in the intestinal epithelium is a key regulator during gastrointestinal infection." (PMID 25799189, 2015). "Thus, Stat3 orchestrates the epithelial response to gastrointestinal infections on multiple levels." (PMID 25799189, 2015). "Although IL-22 has been demonstrated to protect the host from gastrointestinal infections, the functional role of Stat3 in the epithelium has not been demonstrated." (PMID 25799189, 2015).
gastrointestinal stromal tumor (3 papers, 2012 to 2025). "The majority of gastrointestinal stromal tumors (GIST) harbor gain-of-function mutations in KIT or PDGFRA, resulting in the activation of the downstream pathways PI3K/AKT, Ras/MAPK, and JAK/STAT3, and playing a crucial role in tumorigenesis." (PMID 22974104, 2012).
gynecologic cancers (3 papers, 2007 to 2025). "Phosphorylated STAT3 is frequently elevated across gynecologic cancers and drives key oncogenic processes such as invasion and metastasis." (PMID 41463176, 2025). "Future experiments are needed to examine the phosphorylation status of STAT3 and to understand the cell signaling pathways, which are activated by CCL23 in ovarian and other gynecologic cancers." (PMID 41463176, 2025). "Besides, targeting some transcription factors, including STAT3, Wnt, β-catenin, and ZEB1 might be a suitable strategy against gynecologic cancers." (PMID 37310654, 2023).
hearing loss (3 papers, 2014 to 2024). "The levels of the transcription factors, STAT1 and STAT3 (which are associated with cisplatin-induced hearing loss) showed differential regulation, with the levels of STAT1 showing peak increases in 12 h, which diminished over 72 h." (PMID 37063917, 2023).
hemangioma (3 papers, 2016 to 2018). A benign vascular lesion characterized by the formation of capillary-sized or cavernous vascular channels. "Another separate study revealed that propranolol suppressed the expression of phospo-STAT3 in hemangioma cells, making STAT3 an attractive potential therapeutic target." (PMID 29652858, 2018). "STAT3 appears to play a role in IH as phosphorylated STA3 was found to be highly expressed in human hemangioma endothelial cells." (PMID 29652858, 2018). "For example, in human hemangioma and angiosarcoma lesions, high levels of RelA and strong activation of the NF-λB/IL-6/STAT3 signaling axis has been previously reported." (PMID 27105514, 2016).
Hypercholesterolemia (3 papers, 2020 to 2026). An increased concentration of cholesterol in the blood. "Our current results also show that hypercholesterolemia does not affect STAT3 phosphorylation after I/R with or without IPre, thereby providing a deeper insights into the rather unclear effects of metabolic disorders on cardiac STAT3 signaling." (PMID 32466450, 2020).
hypercoagulability (3 papers, 2023 to 2025). "We have now followed many women with STAT3-HIES with IUDs without increased infection risk, and IUDs may be preferable to oral contraceptives due to concerns of hypercoagulability with STAT3-HIES–associated vasculopathy." (PMID 41608118, 2025). "These cytokines are also associated with activation of STAT3 and PAI-1, leading to hypercoagulation in COVID-1927–29." (PMID 37640791, 2023). "Their study revealed that Jianpi Qingre Tongluo Prescription prevents inflammation and hypercoagulability in GA by inhibiting circRNA 104633 and the JAK2/STAT3 pathway, thereby supporting the development of therapeutic targets and drugs for GA." (PMID 41311848, 2025).
inflammatory bone diseases (3 papers, 2022 to 2026). "The JAK2/STAT3 signal transduction pathway is one of the main pathways through which IL-6 exerts its biological roles and plays a critical part in inflammatory bone disease." (PMID 36643585, 2023). "However, in an inflammatory microenvironment, IL-6 is highly expressed by macrophages and potentially triggers STAT3 serine phosphorylation as well as its mitochondrial translocation making it an interesting future target for therapy of inflammatory bone diseases." (PMID 36699722, 2022).
leukocytosis (3 papers, 2022 to 2025). "Janus tyrosine kinase (JAK)-STAT3 signaling dysregulation promotes leukocytosis via IL-6." (PMID 37041610, 2023).
liver dysfunction (3 papers, 2013 to 2023). "These two proteins (NF-κB and STAT3) are likely to play important roles in the liver inflammatory response and in the maintenance of homeostasis, induction of APP synthesis by stimulating cytokines such as IL-6 and TNF-α, and in inducing liver dysfunction." (PMID 23516407, 2013).